LAG3 (lymphocyte activating 3)
Diseases named in the same sentence as LAG3 in open-access papers (continued):
Sharing a sentence is not in itself a finding about the gene and the disease.
melanoma (continued). "They concluded that expression of LAG-3 was an independent predictor of worse overall survival, which is similar to findings of other studies, which found that LAG-3 predicted worse overall survival in melanoma and non-small cell lung cancer." (PMID 37999131, 2023). "The prevention of binding between LAG-3 with MHCII with a cyclic peptide, C25, increases IFN-γ secretion and CD8 T cell infiltration and decreases the FOXP3+ Tregs in both in vivo colon–rectal and melanoma models." (PMID 36829496, 2023). "Currently, more LAG-3 immune checkpoint inhibitors (including tebotelimab, relatlimab, IMP321, etc.)have been trialed and presented strong efficacy against solid tumors including melanoma, breast cancer, NSCLC, and gastric cancer." (PMID 36765782, 2023). "Furthermore, our analysis revealed that within B16F10 melanomas HAVCR2 and LAG3 better characterize the development of a dysfunctional CTL phenotype than does the PDCD1/CD274 axis." (PMID 37182110, 2023). "Considering that CYTL1 may be a potential oncogene in melanoma, it was assessed how CYTL1 interacted with PDCD1, CD274, HAVCR2, TIGIT, SIGLEC15, CTLA4, LAG3, and PDCD1LG2." (PMID 37745303, 2023). "Moreover, the possible interaction between LAG-3 and other checkpoints, namely PD-1 and CTLA-4, holds significant promise in raising the bar and extending the landscape of melanoma immunotherapy." (PMID 37484526, 2023). "In this study, we take a systems biology approach to compare the importance of cytolytic versus IFNG-mediated cytostatic effects in a murine melanoma model (B16F10) and to dissect the contribution of immune checkpoints HAVCR2, LAG3, and PDCD1/CD274 to CTL exhaustion." (PMID 37182110, 2023). "In addition to PD1/PD-L1, CTLA-4, LAG-3, TIM-3, and TIGIT are potential melanoma checkpoints in the future." (PMID 37388230, 2023). "However, our results indicate that LAG-3 and TIM-3 expression levels are low in melanoma cells, making it harder to observe changes in expression." (PMID 37895833, 2023). "Similar to LAG-3, TIM-3 expression is upregulated following treatment of melanoma and non–small cell lung cancers with anti–PD-1 antibodies, which may be one of the reasons for the development of acquired resistance." (PMID 35037899, 2022). "LAG3 binds to MHCII on APC and downregulates T cell function, but it has several other ligands including galectin-3, liver sinusoidal cell lectin (expressed by melanoma cells) and Fibrinogen-like Protein I." (PMID 35054292, 2022). "A novel checkpoint target, LAG-3, emerged, and in melanoma, a drug acting on LAG3, relatlimab, hailed the first non-CTLA-4, PD-1, or PD-L1 targeting approval based on the RELATIVITY-047 trial." (PMID 36290818, 2022). "For this purpose, TMB, LAG3, and PD-L1 expression have been retrospectively evaluated in several solid tumors establishing the rationale to design clinical trials with concurrent inhibition of LAG3 and PD-1 results in a significant advantage in PFS and OS in advanced melanoma patients." (PMID 36013315, 2022). "Interestingly, LAG-3 and MHC-II interaction can downregulate T cell proliferation and protect melanoma cells from drug-induced apoptosis." (PMID 36077354, 2022). "Interestingly, such an immunomodulatory effect involves the inhibition of the checkpoint molecules LAG-3 and TIM-3, which are currently investigated as important therapeutic targets for melanoma treatment." (PMID 35419291, 2022). "Among them, an anti-lymphocyte activation gene-3 (LAG-3) Ab, relatlimab, is another ICI that could be combined with nivolumab for the treatment of untreated advanced melanoma." (PMID 36555362, 2022). "Perhaps, under weak immunogenic conditions (e.g. in the presence of a B16 melanoma) there is no clear LAG-3−/− phenotype." (PMID 35265944, 2022).
melanoma (continued). "In our current analyses, we found that pyroptosis is significantly associated with the increased expression of multiple immune checkpoint factors in the melanoma microenvironment, such as PD-1/PD-L1, CTLA4, TIM3, LAG3, and immune activation-related molecules, including OX-40, CD40, and CD86." (PMID 36513682, 2022). "Furthermore, it was shown that interaction between melanoma cells and activated lymphocytes via MHC-II/LAG-3 resulted in suppression of T-cells." (PMID 35655709, 2022). "We further discovered that PDCD1, CTLA4, TIM-3, LAG3, and RTP4 were upregulated in melanomas." (PMID 34154655, 2021). "Anti-LAG-3 agents are under investigation in phase I–III trials in a wide array of solid tumors including lung, gastric, head and neck, hepatocellular and renal cancer as well as lymphoma and melanoma." (PMID 33651248, 2021). "A recent study in a mouse melanoma model demonstrated that the frequency of CD8+ T cells expressing exhaustion markers (PD-1, TIM3 and LAG3) were significantly higher both at the tumor site and systemically in obese mice compared to their lean counterparts implicating leptin as the mediator." (PMID 32549336, 2020). "Like LAG3, FCRL6 was more highly expressed by MHCII+ melanomas and NSCLCs." (PMID 33162991, 2020). "Similar to the results for Tim-3 and LAG-3, previous findings have indicated that co-blockade of TIGIT and PD1 additively improved CD8+ TIL proliferation, cytokine production, and degranulation in melanoma patients." (PMID 32944390, 2020). "In a previous study no tumor cell-intrinsic LAG3 protein expression was detected in brain metastases from melanoma patients." (PMID 32861198, 2020). "Similarly, the interaction of LAG-3, expressed on T-lymphocytes, with MHC molecules present on melanoma cells, activates ERK1/2, promoting both increased melanoma cell proliferation and immune-escape." (PMID 31117237, 2019). "LAG-3+ TIL numbers are increased in MHC-II+ tumors (lung cancer, melanoma, and breast cancer), and MHC-II+ tumors acquire immunosuppressive signals through LAG-3; thus, combined PD-1/PD-L1 and LAG-3 blockade can provide a particular advantage against MHC-II+ tumors." (PMID 31681269, 2019). "Preliminary results of one such clinical trial demonstrates striking efficacy of LAG3+PD1-blockade (BMS-986016 and nivolumab, respectively) for treatment of advanced melanoma patients whom PD1/PD-L1-blockade previously failed (16% objective response rate and 45% disease control rate)." (PMID 30653605, 2019). "This is consistent with Camisaschi’s study that LAG3 were highly expressed in Treg cells in peripheral blood, tumor-involved lymph nodes and within tumor tissues isolated from patents with advanced (stage III and IV) melanoma and colorectal cancer." (PMID 31783776, 2019). "LAG-3 is known to inhibit APC activation, and in melanoma, MHCII expression was correlated with apoptotic resistance, possibly via LAG-3 engagement suggesting that anti-LAG-3 could be an important therapeutic strategy in MHC II expressing tumors." (PMID 29721192, 2018). "TIM-3 and LAG-3 are also highly expressed other malignancies, e.g., non-small-cell lung carcinoma and melanoma." (PMID 30366424, 2018). "A previous study has shown that anti LAG-3/anti PD-1 combinatorial immunotherapy was not effective against established B16 melanoma tumours, as opposed to fibrosarcoma and colorectal adenocarcinoma tumour models." (PMID 28537896, 2017). "Nevertheless, the LRP analyses detected IDO1, LAG3, TIM-3, VISTA, and CD40 in the 22 melanomas." (PMID 28546465, 2017). "Recent studies have reported that CD8+ TILs from melanoma patients expressed high levels of inhibitory receptors such as programmed cell death protein-1 (PD-1), T cell immunoglobulin and mucin domain-3 (TIM-3), and lymphocyte activation gene-3 (LAG-3)." (PMID 27057178, 2016).
melanoma (continued). "The circulating and tumor-infiltrating iNKT cells from melanoma patients showed elevated proportions of iNKTreg cells and exhibited higher levels of activation markers, NKR/NKG2 (such as NKG2A, NKG2C, and NKG2D), and ICP (particularly ICOS, TIM3, and/or LAG3) compared with the control groups." (PMID 41562072, 2025). "Indeed, immune checkpoint molecules such as TIM3, LAG3 and TIGIT may also be epigenetically regulated and play a role in melanoma prognostication." (PMID 40307913, 2025). "This phase II trial explored whether dual ICI, targeting both LAG-3 (lymphocyte-activation gene 3) and PD-1, could provide improved clinical benefit over PD-1 inhibition alone in patients with resectable clinical stage III or oligometastatic stage IV melanoma." (PMID 40647451, 2025). "The approval of relatlimab (RELA), a lymphocyte activation gene 3 protein (LAG-3) antibody, in combination with nivolumab (NIVO), a PD-1 inhibitor, marked a significant stride toward enhancing treatment efficacy for metastatic and unresectable stage 3 and 4 melanoma." (PMID 39293068, 2024). "Coculture with the A2+/NY+ melanoma cell line A375 revealed consistently higher upregulation of the activation markers CD69 and CD137 as well as of the inhibitory markers lymphocyte-activation gene 3 (LAG3) and programmed cell death protein 1 (PD-1) for CD8+ A97L–T cells as compared with WT." (PMID 38828721, 2024). "At present, relatlimab is the most developed anti-LAG-3 antibody, and a randomized double-blind phase II/III trial (NCT03470922) is currently investigating its effectiveness in combination with anti-PD-1 antibodies, principally nivolumab, in several tumor models, including melanoma." (PMID 38732242, 2024). "Recently, a phase II study [NCT04623775], PD-1 plus chemotherapy with or without LAG3 (n = 520), reported positive results, which may expand recent positive results in first-line melanoma plus PD-1 inhibitors." (PMID 38241591, 2024). "During treatment, higher proportions of 41BB+ Tconv cells, LAG3+ γδ2–T and TIGIT+ iNKT cells were observed in R compared to NR patients, while frequencies of GITR-expressing γδ2–T and iNKT, 41BB-expressing NKbright and CD27-expressing NKdim cells were decreased in responder melanoma patients." (PMID 39687620, 2024). "Interestingly, Gal-3 binds lymphocyte-activation gene 3 (LAG3), the immune checkpoint of immune effector cells, and anti-LAG-3 (relatlimab) represents a novel FDA-approved inhibitor for combinational checkpoint therapy in melanoma." (PMID 36982699, 2023). "Cancers with the greatest proportion of high LAG-3 transcripts were neuroendocrine (47% of patients) and uterine (42%); colorectal had among the lowest proportion of high LAG-3 expression (15% of patients) (all p < 0.05 multivariate); 50% of melanomas were high LAG-3 expressors." (PMID 37132280, 2023). "An in-vitro study on B16 melanoma cells showed that LAG-3/LSECtin interaction can inhibit IFN-γ production and disrupt tumor-specific effector responses, which, in turn, may be reversed by LAG-3 blockade." (PMID 37345056, 2023). "Following the FDA approval of Ipilimumab (a CTLA-4 inhibitor) for advanced melanoma in 2011, ICIs quickly gained approval for treating various cancer types, as evidenced by several FDA-approved immune checkpoints such as PD-1 and its receptor PD-L1, CTLA-4, and LAG3." (PMID 37600822, 2023). "Importantly, LAG3 expression was more abundant than PDCD1 expression in all major TIL subsets in melanoma, unlike in other cancers." (PMID 36719749, 2023). "A similar result was obtained in urothelial, melanoma, and non-small cell lung carcinoma in which IFN-γ signaling-related genes, including IFNG, CD274, LAG3, and CXCL9, could well predict about who could benefit from the immunotherapy via anti-PD-L1/PD-1 antibody." (PMID 37637034, 2023).
melanoma (continued). "Furthermore, LAG-3 is expressed on CD4 (+) CD25 (high) Foxp3 (+) T cells, which represent an expanded cell subset that secretes immunosuppressive cytokines such as IL-10 and TGF-β1 in patients with melanoma and colorectal cancer." (PMID 36829496, 2023). "In a phase 1 trial of patients with melanoma patients and who received melanoma antigen recognized by T-cell 1 (MART1) peptide vaccinations with or without IMP321, those treated with IMP321 presented decreased expression of PD-1, LAG-3, TIM-3, CD244, and CD160." (PMID 37509517, 2023). "Furthermore, expression of LAG-3 on regulatory CD4 T cells identified a more immunosuppressive phenotype, which subsequently hindered CD8 T cell function in Hodgkin’s lymphoma, melanoma and colorectal cancer." (PMID 36445478, 2023). "Additionally, the potential value of various new inhibitory immune checkpoints (BTLA, B7 family, IDO-1, LAG-3) and costimulatory molecules (GITR, ICOS, OX40, 4-1BB, CD40, CD27) has been confirmed for melanoma treatments." (PMID 36125617, 2022). "Given TRM widely express CTLA-4, PD-1 and LAG-3, which are inhibited by immune checkpoint inhibitors such as ipilimumab, nivolumab, pembrolizumab and relatlimab provides a strong biological rationale this CD8 subset is critical in facilitating anti-tumor responses in melanoma." (PMID 36466880, 2022). "The high potential of LAG-3 blockade for cancer therapy is evidenced by the results in melanoma patients, who progressed despite previous immunotherapy not related to LAG-3 and who showed an 11% objective response rate when treated with relatlimab, with 1 complete and 6 partial responders." (PMID 33712537, 2021). "Melanoma cells induce Tregs to overexpress various inhibitory checkpoint receptors, including programmed cell death protein 1 (PD-1), CTLA-4, T cell immunoglobulin and mucin domain-containing protein 3 (TIM-3), LAG-3, and T cell immunoglobulin and ITIM domain (TIGIT)." (PMID 34806028, 2021). "Preclinical studies have demonstrated the efficacy of targeting LAG-3 in combination with immune checkpoint receptors in EOC, and Phase I/II development of a LAG-3 monoclonal antibody is currently being investigated in pancreatic, breast, melanoma, and other solid tumors, including ovarian cancer." (PMID 33747935, 2021). "LAG-3 blockades, Relatlimab [humanized anti-LAG-3 monoclonal antibody (mAb)], and Eftilagimod alpha (a soluble LAG-3 protein) combined with PD-1 inhibitors achieved an ORR of 15% in previously treated melanoma and 52.9% in treatment-naïve advanced NSCLC, respectively." (PMID 33194652, 2020). "Notably, the simultaneous blockade of LAG-3 and PD-1 has shown striking clinical results in melanoma patients that were not responding well to initial PD-1 or PD-L1 monotherapy." (PMID 33374804, 2020). "Moreover, at day 14 after melanoma cell transplantation, tumours from vaccinated mice showed increased absolute numbers of CD8+ TIL expressing PD-1, Nrp-1 and Tim-3 and, to a lesser extent, CTLA-4 and LAG-3." (PMID 31350404, 2019). "Importantly, the combination of anti-LAG-3 (BMS-986016) and anti-PD-1 (nivolumab) antibodies has been shown to be effective in melanoma patients resistant to anti-PD-1/PD-L1 therapy, and is currently being tested in other tumor types (NCT04082364, NCT01968109)." (PMID 31717326, 2019). "Similarly, a 4-1BB agonist was more effective than an anti-LAG-3 blocking antibody as a combination partner for PD-1 blockade in a melanoma mouse model in the absence of any cancer vaccine." (PMID 29535740, 2018). "While LAG-3−/−PD-1−/− mice developed autoimmunity due to lack of self-tolerance, they showed markedly increased survival and clearance of transplanted B16 melanoma or MC38 colon carcinoma." (PMID 27835902, 2016). "Finally, anti-LAG-3 ICT alone conferred no efficacy against B16F10 melanoma." (PMID 38349406, 2024).
melanoma (continued). "Moreover, recently, a new generation of ICIs, namely, the inhibitors of the lymphocyte-activation gene 3 (LAG-3), applied in combination with PD-1 inhibitors, has yielded very promising results and has been added in the therapeutic armamentarium for patients with metastatic or unresectable melanoma." (PMID 37452874, 2023). "In B16 melanoma tumors, dual LAG-3 and PD-1 depletion on TILs diminished tumor-induced tolerance and yielded higher responses compared to single-checkpoint-deficient mice, eliminating 80% of tumors (vs. 40% elimination in PDCD1−/−, and no tumor growth control in wild-type and LAG-3−/−mice)." (PMID 37345056, 2023). "LAG-3 positive T cells are present amongst tumor-infiltrating leukocytes within melanoma, leading to the hypothesis that inhibition of LAG-3/MHC II binding will result in improved immune response, T cell proliferation, and ultimately immune destruction of melanoma cells." (PMID 36831449, 2023). "Nevertheless, it is possible that - if TIM-3 and LAG-3 present a reduced expression in immune cells that were exposed to the secretome of melanoma cells subjected to inflammatory conditions -, they might not be the most effective targets to be explored in the clinic." (PMID 35419291, 2022). "Thus, our current study explores whether the expression of four checkpoint markers (PD-L1, PD-1, LAG-3, and TIM-3) differs in extracranial melanomas versus the subsequent brain metastases, which may shed further light on the mechanism behind CNS-mediated immune suppression." (PMID 31938638, 2019). "Our results highlight the distinct proteomic immune signatures, such as an upregulation of EDAR and downregulation of LAG3, in responders among VLD melanoma patients in comparison to non-responders." (PMID 36230498, 2022). "Previous reports have shown enhanced anti-tumor activity by combinatorial treatment with both anti-LAG3 and anti-PD1 antibodies in murine colon cancer but not in melanoma." (PMID 26318293, 2015). "Although we revealed MHC II expression on melanoma cells and LAG‐3 on NK‐cells, we could not detect any differences in NKmK by blocking LAG‐3." (PMID 41078003, 2025). "Conversely, in ICB-resistant cases, such as Patient 13, melanoma cells lacked MHC class I expression and melanocytic markers and CD8+ T cells failed to express activation or checkpoint markers (e.g., PD1, LAG3, TIM3), suggesting a dysfunctional immune microenvironment." (PMID 41432764, 2025). "Notably, 2xAARE-YB-CAR-Jun-T cells were more efficient at killing CD19+ melanoma cells than 2xAARE-YB-CAR-T cells were and slightly decreased the expression of the exhaustion marker PD-1 without notable effects on LAG-3 and TIM-3." (PMID 40335738, 2025). "A cross-indication biomarker analysis is underway to compare the immune microenvironments of responsive and non-responsive tumors (for example, melanoma versus NSCLC/ESCC), with the aim of elucidating determinants of heterogeneity in patient response to dual PD-1/LAG-3 blockade." (PMID 40993242, 2025). "In congruence with murine T cells, dysfunctional (PD-1+LAG-3+) human CD8+ T cells expressed higher levels of lipid peroxidation– and ferroptosis activation–related genes than nondysfunctional CD8+ T cells in melanoma patient tumor tissues." (PMID 35192544, 2022). "Our results suggest that high plasma CD27s levels predict poorer efficacy of anti-PD1 monotherapy in melanoma but not for the combination therapy, supporting the need for therapeutic escalation with the anti-PD1 and anti-CTLA4 combination or other combination (anti-Lag3)." (PMID 40148586, 2025). "In contrast to HAVCR2 and LAG3, the dynamics of PDCD1 and CD274 did not coincide with the dynamics of CTL exhaustion, suggesting a relatively minor role for PD-1/PD-L1 as determinants of CTL exhaustion in the B16F10 melanoma model, at least at late stages of anti-tumour immune responses." (PMID 37182110, 2023).